EGFR (epidermal growth factor receptor)
Diseases named in the same sentence as EGFR in open-access papers (continued):
Sharing a sentence is not in itself a finding about the gene and the disease.
cancer (continued). "Id-1 mediated cancer cell growth has been shown to be associated with EGFR activation in ovarian and prostate cells." (PMID 19014499, 2008). "EGFR is associated with oncogenic transformation, and dysregulation of EGFR is associated with all of the key features of cancer." (PMID 18991714, 2008). "Although no other statistically significant association was found, it is interesting to notice that EGFR alterations occur mainly in carcinomas of the diffuse type." (PMID 18199332, 2008). "Subsequent studies have identified this subset as patients with cancers driven by mutationally activated EGFR." (PMID 17667926, 2007). "Since loss of E-cadherin and increased EGFR signalling are known markers of invasive mesenchymal cancer cells, we asked if the E-cadherin re-expression and EGFR decreases were accompanied with another known epithelial cell marker." (PMID 17406365, 2007). "In the present study, we used a group of cancer cell lines with overexpressed EGFR or tyrosine kinase domain-mutated EGFR to determine the association of the cellular responses with response markers to EGFR-targeted therapy with cetuximab and gefitinib." (PMID 17931419, 2007). "In conclusion, the present study found an association between EGFR and cancer cell proliferation biomarker Ki-67 in OS patients, and this association was carried by the p-AKT." (PMID 19662227, 2007). "In cancers that have mutations in EGFR, signaling is overactive so the cancer cells divide much more than they should." (PMID 17973573, 2007). "Mutations of the epidermal growth factor receptor (EGFR) are a possible molecular target for cancer therapy." (PMID 17437646, 2007). "A few studies have investigated the association between EGFR polymorphisms and the risk of human cancer." (PMID 17956637, 2007). "Two recent studies evaluated biochemical changes in cell signaling after cetuximab and gefitinib treatment in association with therapeutic responses of several EGFR wild-type and tyrosine kinase domain-mutated cancer cell lines." (PMID 17931419, 2007). "In some NSCLCs, EGFR drives uncontrolled cell division because its tyrosine kinase is mutated and the cancer becomes dependent on or “addicted” to EGFR signaling for its survival." (PMID 17973572, 2007). "To this end, we used site-directed mutagenesis to introduce cancer-associated mutations into an YFP-tagged fragment of EGFR intracellular domain (YFP-EGFR-ICD)." (PMID 17877814, 2007). "Our data suggest that a decrease in HIF-1α levels is indicative of positive responses to EGFR-targeted therapy of cancer cells with either wild-type or tyrosine kinase domain-mutated EGFR." (PMID 17931419, 2007). "Many of the oncogenic effects of MUC1 stem from its cytoplasmic tail, which binds to several proteins implicated in cancer, including c-Src and the epidermal growth factor receptor (EGFR) family." (PMID 16846534, 2006). "Consistent with the role in liver regeneration, nuclear EGFR accumulation is associated with increased proliferation in cancer cells and hepatocytes." (PMID 16434982, 2006). "Nonetheless, overexpression of EGFR observed in human breast/ovarian tumours is associated with poor prognosis with cancer patients." (PMID 15655552, 2005). "Epidermal growth factor receptor is also a cellular receptor for human cytomegalovirus, a cancer-causing virus that causes severe and fatal disease in immune-comprimised individuals." (PMID 15655552, 2005). "As well as interactions with HER2 and other EGFR receptor family members, a number of other factors influence EGFR signalling in cancer cells, such as receptor mutations and increased expression of ligands." (PMID 15187994, 2004). "Individual cancer cells exhibited one of three staining patterns: nuclear staining only (ER+/EGFR-), membrane-associated and cytoplasmic staining only (ER-/EGFR+) or no staining (ER-/EGFR-)." (PMID 8198966, 1994).
cancer (continued). "While prior studies have linked CD73 expression to EGFR‐driven signaling and poor prognosis in cancer patients, our findings delineate the precise molecular mechanism underlying CD73 upregulation in EGFR‐mutant NSCLC and confirming its pivotal role in shaping an immunosuppressive TME." (PMID 41144813, 2026). "Finally, we apply ESPLSM to a cancer cell line dataset to investigate the role of RNA expression in mediating the effect of EGFR mutations on drug responses." (PMID 41851029, 2026). "Consequently, EGFR 20 insertion-mutated cancer cells exhibit increased surface CD54 expressions, increasing their vulnerability to cell lysis." (PMID 40385479, 2025). "Aberrant activation of EGFR signaling is associated with many types of cancers." (PMID 39838173, 2025). "The frequency of five clinically relevant alternate transcripts, including androgen receptor variant 7 (ARv7), hepatocyte growth factor receptor exon 14 skip (METe14), and epidermal growth factor receptor variants (EGFRv) vIII/vIVa/vIVb, was determined overall and by cancer type." (PMID 40711866, 2025). "EGFR mutations correlate with sensitivity to EGFR tyrosine kinase inhibitors (TKIs), highlighting the importance of accurate mutation detection for personalized cancer therapy." (PMID 40515576, 2025). "The national comprehensive cancer network (NCCN) guideline v1.2021 explicitly states that while the frequency of EGFR mutations in LUSC is lower than that in adenocarcinoma, the expert panel recommends that molecular testing should be considered for all patients with LUSC." (PMID 40969259, 2025). "Importantly, we observed a few examples of multiple genes in the same pathway associated with ancestry, as well as a case of EGFR mutations seen across multiple cancer types in the same ancestry group." (PMID 41162424, 2025). "Furthermore, BRAF and EGFR mutations are critical for optimizing targeted therapies in cancer patients." (PMID 40283283, 2025). "Moreover, recent reports have indicated that altered glycosylation on ABC transporters and EGFR, as well as integrin, is associated with cancer chemoresistance." (PMID 40243917, 2025). "Therefore, clinical interpretation of Hub-EGFR.Sig as a biomarker requires careful consideration of both the specific cancer type and underlying molecular context." (PMID 40574864, 2025). "Activation of bypass signaling (via amplification or mutations of HER2, FGFR1, MET, and PDGFR) or downstream signaling (via mutations of NRAS, BRAF, PIK3CA, or deletion of PTEN) in cancer cells has been shown to contribute to resistance to anti-EGFR antibodies." (PMID 40362183, 2025). "However, patients with mutations in the phosphatidylinositol 3-kinase (PI3K) pathway have shown poor response to irreversible EGFR-TKIs because these mutations activate signals that continue to promote cancer cell growth, even when EGFR is blocked." (PMID 40864738, 2025). "Previous research has established that the primary cause of NSCLC is often mutations in the EGFR gene, which result in excessive intracellular signaling and uncontrolled cancer cell proliferation, as well as the development of resistance to EGFR-targeted therapies." (PMID 40076971, 2025). "Other studies suggest that using bispecific antibodies in combination with other cancer therapies can be more effective in treating cancer and reduce the risk of resistance as it is designed to detect EGFR and EPHA2 proteins, which are located on the cancer cells’ surface." (PMID 40650799, 2025). "Indeed, EGFR showed positive interaction effects for mutations and CNVs in multiple cancer types, including LUAD." (PMID 41415395, 2025).
cancer (continued). "The current network pharmacology-based analysis of A. laxiflora suggested that compounds (quercetin, 3-acetylursolic acid, and 3-acetyloleanolic acid) in this plant can influence key cancer-associated targets EGFR, AKT1, SRC, and MAPK1 through the PI3K-Akt, MAPK, Ras, and Rap1 signaling pathways." (PMID 40283942, 2025). "Also, this study suggested the diagnostic use of EGFR(Y1068) phosphorylation in screening cancers sensitive to CAP treatment and brought hope for cancer patients harboring the intact EGFR(Y1068) site." (PMID 39781456, 2025). "ExoDx Lung (ALK) accurately identifies the EML4-ALK mutation in cancer cells by analyzing exosomal RNAs in the blood, while ExoDx Lung (T790M) detects the EGFR T790M mutation, and ExoDx Lung (EGFR) identifies both EGFR activation and T790M resistance mutations." (PMID 41573685, 2025). "This drug has been used to treat many types of cancer with EGFR mutations effectively." (PMID 40864738, 2025). "The L858R mutation in exon 21 of EGFR is a prevalent mutation in cancer cells." (PMID 40449599, 2025). "Importantly, several pathways, such as the TGF-β and EGF/EGFR signaling pathways, which are closely associated with cancer progression and metastasis, were found to be highly enriched with ADSCs-EVs treatment." (PMID 39759123, 2025). "Research has demonstrated that high-level expression of MUC1, through its involvement in the NF-κB and MAPK signaling pathways, could activate the EGFR signaling cascade, which linked to cancer stem cell characteristics." (PMID 40655139, 2025). "Additionally, the pathway is linked to resistance against various cancer treatments, including chemotherapy and targeted therapies like Epidermal Growth Factor Receptor (EGFR) inhibitors." (PMID 40075700, 2025). "EGFRvIII, a common mutant form of EGFR, is implicated in cancer metastasis, including BC." (PMID 40281554, 2025). "Epidermal growth factor receptor (EGFR) and human epidermal growth factor receptor 2 (Her2) are tyrosine kinases, and mutations causing upregulation or amplification are associated with a number of cancers." (PMID 40277814, 2025). "In addition, restoring miR-16 in NSCLC cells not only inhibits key oncogenic pathways such as ERK/MAPK but also renders the cancer cells more susceptible to cisplatin and EGFR inhibitors in xenograft models." (PMID 40978098, 2025). "Additionally, although the anticancer activity and associated mechanisms of EGFR-TKIs in other cancers have been well understood, supportive preclinical studies for the clinical potential of EGFR-TKIs in HNC are lacking." (PMID 38888847, 2025). "For instance, EGFR, a tyrosine kinase receptor commonly upregulated and mutated in cancer, triggers an oncogenic pathway that fosters cancer cell survival and proliferation, through the activation of the PI3K/Akt and RAS–MAPK–Erk signaling pathways, respectively." (PMID 41009395, 2025). "Compared with mice with mutated hKRAS, the EGFR (Del19) mice showed a much lower cancer burden and a longer process from initiation to early development of adenocarcinoma, which is conducive to observing the occurrence of carcinoma and evaluating the safety of MSCs in tumorigenesis." (PMID 40892007, 2025). "EGFR amplification leads to autophosphorylation of receptor tyrosine kinases, triggering downstream signaling pathways that regulate cell proliferation, differentiation, and survival, and is implicated in the pathogenesis of various human cancers." (PMID 40575167, 2025). "EGFR is a proto-oncogene that is mutationally activated in a variety of cancers." (PMID 40291701, 2025).
cancer (continued). "Epidermal growth factor receptor (EGFR) is a major driver of cancer dissemination and target for anti-cancer therapies but the molecular mechanisms underlying its oncogenic roles remain unclear." (PMID 39838173, 2025). "Utilizing the Cancer Dependency Map (DepMap), we first analyzed whether the loss of EGFR (via CRISPR Public 22Q4 datasets) in over 1000 cancer cell lines requires agrin as a co‐dependent gene for regulation of cellular proliferation." (PMID 40165020, 2025). "In addition, the massive accumulation of ROS inhibits the EGF and EGFR-mediated cell proliferation pathways, causing cancer cell cycle arrest." (PMID 41154590, 2025). "Therapies targeting EGFR pathways in IBD may help reduce long-term cancer risk by optimizing the response to chronic inflammation." (PMID 40102272, 2025). "For early detection, it identifies cancer-specific mutations, such as EGFR mutations, at an early stage through a non-invasive method using tumor-derived EVs, making it ideal for screening high-risk groups like smokers or those with a family history of cancer." (PMID 40206799, 2025). "Given that apoptosis-associated proteins are involved in multiple cancer signaling pathways, we combined with network pharmacological analyses to speculate that Dio may interact with EGFR and CASP3 in GBM." (PMID 40391080, 2025). "Besides being the first to document CAP-triggered ferroptosis of TNBC cells, this study for the first time associated EGFR(Y1068) with cancer cell ferroptosis." (PMID 39781456, 2025). "For example, PTEN loss may render cancer cells less susceptible to the pro-apoptotic effects of EGFR inhibitors by activating the PI3K/AKT and other anti-apoptotic pathways." (PMID 40129883, 2025). "Consequently, current cancer immunotherapies have failed in patients with EGFR mutations, while patients with KRAS mutations have more favorable outcomes." (PMID 40524071, 2025). "For example, erlotinib, the first TKI for NSCLC patients who carry the L858R mutation in EGFR, dramatically inhibited the proliferation of cancer cells, thereby shrinking tumors and extending the lives of patients when concurrently used with chemotherapeutic drugs." (PMID 40649937, 2025). "The disruption of the EGFR mutant allele was essential for NSCLC cell killing effect which indicated that the mutant-specific Cas9 allele can effectively differentiate the mutant EGFR allele from the wild-type allele, leading to targeted disruption of the oncogene and cancer cell death." (PMID 40428391, 2025). "In the literature, EGFR activation has been associated with cancer-related neuropathic pain; therefore, EGFR inhibition may represent a potential therapeutic approach for certain types of pain." (PMID 40724945, 2025). "Furthermore, cancer patients in the total ICI cohorts were divided into two subgroups according to the risk scores of Hub-EGFR.Sig, and Hub-EGFR.Sig gene expression varied between the two groups." (PMID 40574864, 2025). "Importantly, AREG overexpression has been identified as a key mechanism underlying resistance to EGFR inhibitors such as gefitinib in non-small-cell lung cancer and other cancer types." (PMID 40725192, 2025). "In this study, structural changes in the extracellular domain of EGFR with the R497K mutation, which may be associated with Cetuximab resistance in cancer patients, were investigated via molecular modeling." (PMID 40332084, 2025). "Consequently, EGFR’s characteristics make it a dependable diagnostic biomarker for cancers where it is involved, mainly lung and breast cancer." (PMID 41440247, 2025). "However, it is important to note that the frequency of these mutations in ATC is low compared to other types of cancer where EGFR mutations are more prevalent, such as non-small cell lung cancer." (PMID 39744583, 2025).
cancer (continued). "The REFRACT study conducted a retrospective analysis of data from 12 Chinese cancer research institutions, and the results showed that among patients with locally advanced EGFR mutation NSCLC, first-line use of RT+TKI± chemotherapy was associated with better PFS and OS." (PMID 40071087, 2025). "EGFR/ErbB-1 is also implicated in carcinogenesis in several carcinomas." (PMID 40422510, 2025). "This excess in EGFR mutations was consistent in multiple other cancer types (though not all types), including lung, breast, prostate, kidney, and unknown primary carcinomas." (PMID 41162424, 2025). "Additionally, EGFR demonstrates varying rates of mutation in cancer when considering race and ethnicity, with evidence for a higher incidence of EGFR mutations in Puerto Rican patients compared with Caucasian patients." (PMID 38732165, 2024). "Furthermore, compound III exhibited antibreast cancer activity associated with EGFR inhibition with an IC50 value of 31.80 nM." (PMID 39780846, 2024). "In addition, CDX2-suppressed cancers had a higher prevalence of mutations in several receptor tyrosine kinase genes, including EGFR, ERBB3, ERBB4, RET, and ROS1." (PMID 39452477, 2024). "Testing for specific variants has become standard of care in many cancers (e.g., EGFR analysis in non-small cell lung cancer), but next generation sequencing has enabled the ability to examine hundreds of genes and biomarkers that are implicated in cancer biology." (PMID 38461318, 2024). "The overexpression and mutation of the EGFR have been associated with cancers." (PMID 38601214, 2024). "Gene Ontology Enrichment Analysis (GOEA) of the 221 up-regulated genes in the afatinib-tolerant cell population revealed several biological processes associated with resistance to EGFR inhibitors in other cancer types, such as oxidative phosphorylation and fatty acid metabolism." (PMID 38605363, 2024). "EGFR is itself frequently mutated or amplified in cancer patients, particularly in NSCLC." (PMID 38668053, 2024). "EGFR is a receptor tyrosine kinase commonly associated with cancer progression and poor prognosis." (PMID 39723390, 2024). "However, the use of EGFR-TIK frequently leads to mutations in EGFR, including T790M, L1196M, and T529N, and activation of the autophagy pathway, resulting in drug resistance in cancer cells." (PMID 39019857, 2024). "Furthermore, disrupting the interaction of CBL mutations with EGFR or CIN85 can also reduce the development of cancer." (PMID 39130630, 2024). "It is a member of the human epidermal receptor (HER) family and an important component of the cellular signaling pathway, and the upregulation of both EGFR gene and protein expression levels activate downstream pathways that are associated with cancer progression." (PMID 38576495, 2024). "Defects in EGFR recycling or degradation have been linked to hyperactive EGFR signaling and cancer." (PMID 39141345, 2024). "EGFR is associated with various cancers, often due to mutations that cause continuous activation." (PMID 39211042, 2024). "Furthermore, HSP70 inhibition sensitizes EGFR tyrosine kinase inhibitors (TKIs) in killing EGFR-mutated HCC827 cancer cells in vivo and in vitro." (PMID 39470734, 2024). "Attempts to surmount this therapeutic challenge are hindered by a poor understanding of how and why cancer mutations specifically amplify ligand-independent EGFR auto-phosphorylation signals to enhance cell survival and how this amplification is related to ligand-dependent cell proliferation." (PMID 38503739, 2024). "Moreover, altered EGFR expression has been linked to other human cancers, including breast cancer, glioblastoma, and lung cancer." (PMID 39035991, 2024). "In addition to SIRT1, other hub genes like EGFR have been implicated in autophagy-related pathways, particularly in cancer biology, where EGFR’s role in autophagy regulation is well established." (PMID 39494277, 2024).